TIGIT (T cell immunoreceptor with Ig and ITIM domains)
Diseases named in the same sentence as TIGIT in open-access papers (continued):
Sharing a sentence is not in itself a finding about the gene and the disease.
tumor (continued). "Other studies have also indicated the importance of TIGIT+ NK cells in the tumor microenvironment." (PMID 31681269, 2019). "Interestingly, it was found that there were tumor nodules on the liver surface in 63.64% of 9-month-old HBs-tg mice that were treated with anti-TIGIT mAb in combination with HBsAg vaccination." (PMID 30644386, 2019). "As an important inhibitory receptor, TIGIT may play dual roles in different stages of tumor development." (PMID 30644386, 2019). "A recent study provided evidence that TIGIT blockade may induce anti-tumor immune activity in preclinical models, and its combination with PD-1/PD-L1 inhibitors is being explored." (PMID 31214193, 2019). "Consequently, the distinct roles of TIGIT in the various stages of tumor initiation and progression should be accounted for the use of checkpoint inhibitors." (PMID 31507621, 2019). "Moreover, compartment-specific differences were also found for TIGIT and PD-1 expression levels in these tumours." (PMID 30733837, 2019). "Our study revealed that TIGIT can be highly expressed in the lymphocytes of tumour tissues." (PMID 31090213, 2019). "Whereas activation through DNAM-1 after recognition of CD155 or CD112 enhances NK cell-mediated cytotoxicity against a wide range of tumor cells, TIGIT recognition of these ligands exerts an inhibitory effect on NK cells by diminishing IFN-γ production, as well as NK cell-mediated cytotoxicity." (PMID 31234588, 2019). "It is tempting to speculate that these tumour types may benefit better from future anti-TIGIT therapies than those with lower amounts of TIGIT+ lymphocytes." (PMID 30733837, 2019). "The cytotoxic function of NK cells co-cultured with MDSCs against tumor cells could be restored by blockade of TIGIT." (PMID 31027331, 2019). "Therefore, CD8+ T cells play an important role in adaptive immunity-mediated tumor progression and TIGIT is critical in maintenance of liver tolerance by keeping CTLs in homeostatic balance." (PMID 30644386, 2019). "Furthermore, the blockade of the checkpoint receptor, TIGIT, promotes NK cell-based tumor-specific T cell immunity, further highlighting the contribution of NK cells to the restoration of tumor-specific CD8+ T cell immune responses." (PMID 31787967, 2019). "For example, TIGIT expression on mouse NK cells was up-regulated during tumor progression." (PMID 31552017, 2019). "Monoclonal antibody blocking TIGIT reversed the exhaustion status of tumor infiltrating NK cells." (PMID 31552017, 2019). "CTLA-4 and TIGIT act as tumor suppressors and thus, modulate the immune response in the TME." (PMID 31801611, 2019). "Previous studies have shown that peripheral blood and tumor-infiltrating T cells express differing levels of PD-1, and here we show that this is also true for other T cell co-signaling molecules including 4-1BB and TIGIT." (PMID 30867072, 2019). "Importantly, antibody blockade of TIGIT has shown antitumor activity in preclinical mouse models, highlighting the potential utility of this pathway for tumor immunotherapy." (PMID 30400822, 2018). "Here, we unexpectedly discovered the expression of TIGIT in murine tumor cells." (PMID 30555485, 2018). "Firstly, we demonstrated that tumor cells could intrinsically express TIGIT for the first time, while TIGIT was previously reported to be an inhibitory molecule of immune cells." (PMID 30555485, 2018). "Taken together, our study for the first time discovered that tumor cells could intrinsically express TIGIT." (PMID 30555485, 2018). "Tumor associated lymphocytes expressing TIGIT have so far been demonstrated in acute myeloid leukemia, non-small cell lung cancer, colorectal carcinoma and melanoma." (PMID 30514251, 2018). "Tumor-infiltrating lymphocytes (TILs) from a variety of human tumors, including non-small cell lung cancer, renal cell carcinoma, and colorectal cancer, were analyzed for coexpression of TIGIT and CD226." (PMID 30400822, 2018).
tumor (continued). "The tumor growth inhibition led by TIGIT knockout was significantly rescued in BABL/c nude mice, indicating that impairment of T cell function might be mediated by TIGIT on tumor cells." (PMID 30555485, 2018). "Collectively, these results indicated that tumor-intrinsic TIGIT could promote tumor growth mainly by suppressing the function of CD8+ T cells." (PMID 30555485, 2018). "The widely expression of TIGIT in tumor cells also suggested the distinct function involved." (PMID 30555485, 2018). "In addition, the anti-tumor effects of blocking TIGIT by the antibody or recombinant PVR protein were investigated, and the anti-tumor effects of anti-TIGIT through tumor intrinsic TIGIT were also studied." (PMID 30555485, 2018). "The in vivo efficacy of TJT6 was investigated in MC38 tumor model using human TIGIT knock-in mice." (PMID 30400822, 2018). "Interestingly, TIGIT-expressing CD8+ T cells often co-express the inhibitory receptor PD-1 providing a strong rationale for simultaneously targeting TIGIT and PD-L1 for optimal anti-tumor activity." (PMID 30400822, 2018). "However, we noticed a remarkable decrease of TIGIT expression on tumor cells after exposure to the MVAC chemotherapy regimen in the MB49 model." (PMID 30356816, 2018). "Despite efficacy in certain preclinical tumor models, whether blockade of TIGIT and/or CD96 modulates NK cell effector function and results in clinical responses in human cancer patients remains to be seen." (PMID 30250471, 2018). "Intriguingly, blocking LAG3, TIM3, or TIGIT alone had a minimal impact on tumor growth inhibition, but was active only in combination with anti-PD-L1/PD-1 treatment, suggesting that the suppressive capacity of the PD-1/PD-L1 axis is dominant over other known co-inhibitory receptors." (PMID 29482595, 2018). "Our findings elucidated that tumor-intrinsic TIGIT could help the tumor to grow by suppressing the function of NK and CD8+ T cells, which can be restored by TIGIT antibody or PVR blockade." (PMID 30555485, 2018). "Considering that most of the studies reported that TIGIT function via NK cells, we proposed that NK and T cells might both be inhibited by TIGIT on CT26 tumor cells." (PMID 30555485, 2018). "Additionally, this pathway is expressed mainly by TILs which, similar to TIGIT, allow it to be more tumor-specific and less toxic than other pathways." (PMID 29544515, 2018). "Since TIGIT knockout could inhibit the tumor growth in vivo, it is necessary to investigate whether TIGIT blockade has anti-tumor effects." (PMID 30555485, 2018). "Elevated TIGIT expression in T cells could suppress the anti-tumor immune responses in glioma, which might be a possible mechanism by which sFGL2 promoted tumor progression." (PMID 27732962, 2017). "These interesting findings suggest that F. nucleatum present in the tumor niche may enhance tumor escape by inactivating NK-mediated killing upon interaction of the fusobacterial Fap2 with the inhibitory receptor TIGIT." (PMID 28321417, 2017). "Similarly, CD112, the ligand for both activating receptor CD226 and inhibitory receptor TIGIT in humans, is frequently expressed at high levels on tumor cells." (PMID 28702032, 2017). "Taking into account the crucial roles of TIGIT in immunosuppression, and benefits from TIGIT blocking in animal studies or in vitro experiments, TIGIT blockade alone or together with other coinhibitory molecules would be considered as a potential therapeutic strategy for tumor management." (PMID 29225597, 2017). "Therefore, co-blockade of either TIGIT plus PD-1 or TIGIT plus Tim-3 enhances anti-cancer immunity and induces tumor regression." (PMID 28545567, 2017). "Besides, CD155 and CD112, ligands of TIGIT, are highly expressed on various human tumors besides immune cells, which indirectly suggest the involvement of TIGIT in tumor immunity." (PMID 29225597, 2017). "TIGIT is thought to regulate anti-tumor T cell effector responses in a number of different ways." (PMID 28649381, 2017).
tumor (continued). "TIGIT is highly expressed on TILs in the tumor microenvironment across a broad range of tumors." (PMID 28545567, 2017). "Furthermore, blockade of co-inhibitory molecules of TIGIT and programmed cell death-1 (PD-1) disrupts immune checkpoints and enhances anti-tumor activity." (PMID 26735971, 2016). "Tumor-intrinsic features such as MSI status, mutational burden, co-expression of other immune checkpoints, and differences in treatment exposure may also modulate the biological and clinical significance of the TIGIT/CD155 axis." (PMID 41596586, 2026). "However, the sole blockade of TIGIT showed limited antitumor efficacy, while the blockade of TIGIT in combination with anti-PD-1/PD-L1 therapy showed enhanced antitumor effect in mice even in anti-PD-1-resistant tumor models." (PMID 40003864, 2025). "In colorectal cancer (CRC), the iNKT-neutrophil axis paradoxically suppresses anti-tumor immunity, with tumor-infiltrating iNKT exhibiting a pro-tumorigenic phenotype characterized by GM-CSF and IL-17 secretion and expression of exhaustion markers (PD-1, TIGIT, TIM-3)." (PMID 40718496, 2025). "Moreover, a preclinical study of tiragolumab, an Fc-competent anti-TIGIT antibody, demonstrated that it remodeled the tumor microenvironment by engaging IgG Fc receptors in an animal model, highlighting the potential clinical impact of Fc portion design on clinical outcomes." (PMID 39847233, 2025). "Thus, TIGIT may be an important immunosuppressive molecule related to the immunosuppressive function of Tregs, which are involved in tumor immune escape and resistance." (PMID 40008144, 2025). "Additionally, higher levels of Treg cells were found in the primary tumor tissue, expressing elevated levels of costimulatory genes associated with immune checkpoints (CD27, ICOS, TNFRSF4, and TNFRSF18) and exhaustion markers (CTLA4 and TIGIT)." (PMID 40303346, 2025). "T cell immunoreceptor with immunoglobulin (Ig) and ITIM domain (TIGIT) is a receptor of the Ig superfamily, which is expressed by activated T cells, NK cells, regulatory T cells and follicular T helper cells and limits T cell- and NK cell-mediated tumor recognition." (PMID 40565299, 2025). "These CXCL13+CD8+PD-1+TIGIT+ T cells, referred to as effector-like CD8+ Tex cells, are characterized by robust cytotoxicity, secretion of inflammatory cytokines and chemokines, and strong association with antitumor immune responses, suggesting their involvement in effective tumor control cells." (PMID 40799645, 2025). "To verify whether NLRP4-eco was cancer-type conserved, we examined NLRP4-OE in MC38 cell-line, and confirmed the same anti-tumor capacity mediated by iNOS+ M1, TIGIT+TNFA+ NK and CD103+ DC, along with favorable OS, further emphasizing the unique landscape of NLRP4-eco across different cancer types." (PMID 40087771, 2025). "However, the high expression of PD-1 and TIGIT on CD8 T cells from responders could indicate that the cells were tumor specific and that the T cells were activated." (PMID 40944710, 2025). "Additionally, inhibiting TIGIT enhances tumor-specific T cell immunity through an NK cell-dependent process, improves therapeutic results with anti-PD-L1 antibodies, and extends memory immunity during tumor rechallenge in animals." (PMID 40567374, 2025). "Therefore, TIGIT blockade alone has a limited therapeutic ceiling, emphasizing the need to explore combination therapies with other immune checkpoint inhibitors to maximize NK cell-mediated anti-tumor responses." (PMID 40231264, 2025). "Anti-TIGIT antibodies are being tested in combination with PD-1/PD-L1 inhibitors in mice models, with the combined blockade of TIGIT and PD-L1 signaling resulting in reduced tumor growth, increased effector T cells and subsequently enhanced immune memory effects." (PMID 40868227, 2025).
tumor (continued). "Given its ability to engage both T cell activation and potential ADCC via NK cells, combining cosibelimab with other ICIs, such as CTLA-4 inhibitors or newer agents targeting LAG-3 or TIGIT, could synergistically overcome resistance mechanisms and improve anti-tumor immune responses." (PMID 40299523, 2025). "Additionally, TIGIT inhibition produced strong tumor-specific T cell immunity reliant on NK cells, increased the effectiveness of PD-L1 antibody treatment, and created durable memory immunity in tumor re-challenge animals." (PMID 40567374, 2025). "Consequently, this downregulation may contribute to decreased activation of anti-tumor immune responses via suppression of genes related to TIGIT signaling." (PMID 40565233, 2025). "An Fc-competent PD-L1*TIGIT bispecific antibody promoted greater T cell expansion and tumor cell killing than benchmark antibodies and antibody combinations in an Fc-dependent manner, indicating that the TIGIT-mediated beneficial properties may be related to both T cell and NK cell activation." (PMID 38474651, 2024). "Moreover, Robert F.Schwabe and collogues demonstrate that FN can inhibit the cytotoxicity of NK cells through TIGIT, down-regulate its inhibitory effect on tumor cells, and then promote the occurrence and development of tumors, especially colorectal adenocarcinoma tumors." (PMID 39175566, 2024). "We found a negative correlation between TIGIT positivity on T cells and PD-1 and LAG3 protein levels on tumor-infiltrating immune cells, supporting the hypothesis that TIGIT upregulation may compensate for low expression levels of other immune checkpoint proteins in RCC." (PMID 39105820, 2024). "Thus, blocking TIGIT contributed to NK cell activation in the CRC subcutaneous tumor." (PMID 38543173, 2024). "Comprehensive tumour profiling included whole exome sequencing for tumour mutational burden (TMB) and ultraviolet(UV) signatures, and immunohistochemistry for immune-cell infiltration (CD4/CD3/CD8/CD103/CD20) and immune-checkpoint expression (PD-L1/LAG3/TIGIT)." (PMID 38672534, 2024). "Indeed, immune regulation through TIGIT+ Treg plays a central role in anti-tumor immunity as loss of TIGIT on Treg, but not on other T cells, restores Tcon functions and slows tumor growth in preclinical cancer models." (PMID 39981298, 2024). "Additionally, we analyzed the expression of CTLA‐4, PD‐1, LAG3, and TIGIT, which are inhibitory immune checkpoint molecules expressed in immune cells and exert inhibitory effects on the anti‐tumor functions of effector cells by binding to their respective ligands." (PMID 39659057, 2024). "Therefore, TIGIT blockade alleviates NK cell exhaustion and limits tumor growth." (PMID 38788198, 2024). "However, in humans, Fn abundance within the tumor is inversely correlated with tumor-specific T cell abundances, and in cell culture, Fn directly binds human T cells and inhibits their function, potentially via interactions between TIGIT and Fn adhesin, Fap2." (PMID 38363784, 2024). "The blockade of TIGIT could be a promising alternative to enhance anti-tumor immunity." (PMID 39339180, 2024). "On the other hand, Fap2 of F. nucleatum could interact with TIGIT, an immunoregulatory signaling receptor on NK and T cells, and this Fap2-TIGIT interaction could reduce killing of tumor cells by NK and tumor-infiltrating lymphocytes and inducing lymphocyte apoptosis." (PMID 36407281, 2023). "Moreover, subsequent experiments both in vitro and in vivo confirmed that blocking TIGIT could delay tumor progression and restore the antitumor function of CAR T-cells." (PMID 37149643, 2023). "In addition, TIGIT has been reported to be expressed on tumor cells in mice." (PMID 37670328, 2023). "Hence, the therapeutic elimination of Tregs by means of anti-TIGIT antibody-dependent cytotoxicity may confer a considerable anti-tumor effect." (PMID 37291608, 2023).
tumor (continued). "Thus, the high levels of both CD155 and TIGIT may contribute to create an immunosuppressive environment, representing a mechanism of tumor evasion." (PMID 37629138, 2023). "However, selective inhibition of TIGIT improved anti-tumor immunity in murine models OSCC." (PMID 37221555, 2023). "Future therapies to overcome the inhibitory immune checkpoints beyond CTLA-4 and PD-1/PD-L1, such as therapies targeting LAG-3, TIM-3 and TIGIT, may be clinically beneficial since immune exhaustion and subsequent tumor escape remains critical for RCC progression." (PMID 37173966, 2023). "However, the role of TIGIT in cancer development and progression remains controversial, particularly regarding the relevance of its expression both in the tumor microenvironment and on tumor cells, with prognostic and predictive implications that remain to date essentially undisclosed." (PMID 37109579, 2023). "Therefore, in this study, we focused on TIGIT expression on tumor cells." (PMID 37573372, 2023). "Additionally, CyTOF analysis of tumour samples revealed expression of immune checkpoint (IC) molecules, particularly TIGIT and PD-1 in infiltrating T cells, suggesting a pre-existing immune response, providing the rationale for combination therapy with IC inhibitors and Gsα peptide vaccine in PMP." (PMID 36723696, 2023). "In addition to systemic anti-TIGIT therapies, an oncolytic VV armed with an scFV against TIGIT has demonstrated enhanced anti-tumour efficacy and increased recruitment and activation of T cells within the TME compared to parental virus in several subcutaneous tumour models." (PMID 37627206, 2023). "Furthermore, TIGIT expression was lower in tumor tissues with the treatment of MT CAR-T cells." (PMID 37359558, 2023). "Furthermore, we established tumor‐bearing mouse models and proved that anti‐TIGIT, anti‐CD96, and anti‐PD1 could remarkably inhibit the growth of CC cells in vivo; yet no statistical differences were found between these three groups." (PMID 36725337, 2023). "Additionally, Flt3L therapy enhanced tumor response to RT combined with TIGIT blockade." (PMID 35794399, 2023). "Thus, Whether TIGIT is differentially expressed in the pan-cancer spectrum and whether TIGIT can be used as a tumor marker of pan-cancer is still questionable and needs more exploration in the future." (PMID 37035135, 2023). "Therefore, we hypothesized that anti-TIGIT therapy could enhance immune-mediated responses to RT and synergistically boost anti-tumor effects." (PMID 35794399, 2023). "Also, TIGIT+ NK cells display weaker anti-tumor cytotoxicity than TIGIT− NK cells." (PMID 37291608, 2023). "Moreover, anti-TIGIT inhibitors could prevent T cell exhaustion, reduce tumor cell growth rate, prolong survival, and prevent myeloma escape after stem cell transplantation in mice with MM." (PMID 37291608, 2023). "In addition, the therapeutic response of cancer patients to RT and anti-TIGIT treatment may be strengthened by using Flt3L to boost CD103+ DCs at the tumor site." (PMID 37291608, 2023). "Hence, TIGIT has become a reliable therapeutic target for clinical tumor immunotherapy." (PMID 37106742, 2023). "In addition, we provide greater context for TIGIT expression in the tumour microenvironment which may facilitate a deeper understanding of the mechanistic consequences of blockade." (PMID 37596248, 2023). "Moreover, TIGIT but not CTLA-4 or PD-1 is associated with NK-cell exhaustion in tumor-bearing mice and colon cancer patients." (PMID 35410257, 2022). "We deduced that it may be possible to reverse T cell dysfunction by intervention in these pathways to revive CD8+ T cells against tumor activity (such as TIGIT, TNFRSF9, CTLA-4, LAG3, PD-1), and this approach maybe represented new strategies for immunotherapy against LUAD." (PMID 36483553, 2022).